SNORD62A (small nucleolar RNA, C/D box 62A)
Synonyms: U62; U62A; RNU62
Gene: Small nucleolar RNA gene on chromosome 9 (131,485,665 to 131,485,750, forward strand). Ensembl gene ENSG00000235284.
Gene Ontology:
Biological process: RNA processing
Cellular component: nucleolus
Homologues: Orthologues: chimpanzee SNORD62 (100% identical), macaque SNORD62 (99% identical), rabbit SNORD62A (97% identical), mouse Gm22192 (95% identical), guinea pig SNORD62 (92% identical), pig SNORD62 (90% identical), tropical clawed frog SNORD62 (78% identical), tropical clawed frog SNORD62 (71% identical). Paralogues in human: SNORD62B (100% identical), SNORD62 (85% identical).